TYMS (thymidylate synthetase)
Diseases named in the same sentence as TYMS in open-access papers (continued):
Sharing a sentence is not in itself a finding about the gene and the disease.
acute respiratory distress syndrome (1 paper, 2025). Progressive and life-threatening pulmonary distress in the absence of an underlying pulmonary condition, usually following major trauma or surgery. "In a study on acute respiratory distress syndrome (ARDS), RBP7 was found to be closely associated with CD14 cells, and the high expression of TYMS in both CD14 and B cells suggests a synergistic relationship in regulating immune responses in ARDS." (PMID 41301068, 2025).
alopecia (1 paper, 2024). Hair loss usually from the scalp. "People with the RFC1 80AA genotype were shown to possess a greater prevalence of MTX-related hepatotoxicity and alopecia, while the TYMS 3R3R genotype was linked to a greater danger of bone marrow toxicity." (PMID 38311638, 2024).
aplastic anemia (1 paper, 2022). Anemia resulting from bone marrow failure (aplastic or hypoplastic bone marrow). "Abnormal gene expression exists in children with idiopathic severe aplastic anemia, and RRM2, TTK, and TYMS in children's MSCs are significantly down-regulated." (PMID 35082972, 2022).
astrocytomas (1 paper, 2004). "A restricted set of tumor-associated genes was identified for each grade that included genes not previously associated with astrocytomas (e.g. VCAM1, SMOC1, and thymidylate synthetase), with a high percentage of cell surface genes." (PMID 15265232, 2004).
atopic dermatitis (1 paper, 2026). "The high-affinity binding between methotrexate and GALE substantially exceeds its binding strength with the classical target TYMS, providing a novel theoretical framework for explaining methotrexate’s unique efficacy in atopic dermatitis treatment." (PMID 41556698, 2026). "Our findings establish a causal relationship between specific gut bacteria (Eubacterium eligens group) and atopic dermatitis risk while identifying seven key bridging genes (AKR1C2, GALE, GGH, NR4A1, PLA2G4B, TYMS) that connect gut microbial metabolites to skin pathology." (PMID 41556698, 2026).
atrial fibrillation (1 paper, 2025). A disorder characterized by an electrocardiographic finding of a supraventricular arrhythmia characterized by the replacement of consistent P waves by rapid oscillations or fibrillatory waves that vary in size, shape and timing and are accompanied by an irregular ventricular response. "A recent study validated a set of five differentially expressed and co-upregulated genes (DEGs) (DGAT1, AMOT, PDE11A, TYMS, and TMEM98) that were elevated in patients with atrial fibrillation, liver disease, and atrial fibrillation associated with liver disease compared to healthy controls." (PMID 40141794, 2025).
atrial septal defect (1 paper, 2012). Interauricular communication is a congenital malformation characterized by a communication between the atrial chambers of the heart. "In this study, we investigated the effects of two extensively studied TYMS insertion/deletion sites on CCSDs, including ventricular septal defects (VSDs), atrial septal defects (ASDs) and complex traits composed of VSD and ASD, in a Han Chinese population." (PMID 22384047, 2012).
brucellosis (1 paper, 2024). Brucellosis is a bacterial infection that spreads from animals to people via unpasteurized dairy products or by exposure to contaminated animal products or infected animals. "A proliferative CD8+ T‐cell subset (CD8_Pro), characterized by high expression of MKI67 and TYMS, was obviously increased in acute brucellosis patients." (PMID 39135683, 2024).
carcinoids (1 paper, 2016). "In contrast to carcinoids, carcinomas seem to have faster utilization via TYMS than their uptake can provide." (PMID 27064343, 2016). "In contrast, carcinoids present predominantly with the Ft-phenotype indicating high FOLR1 and FPGS, but low TYMS gene expression levels." (PMID 27064343, 2016).
cardiac septal defects (1 paper, 2012). "To examine the role of TYMS in Congenital Cardiac Septal Defects (CCSDs) risk, we investigated whether genetic polymorphisms in the TYMS gene associated with the CCSDs in a Han Chinese population." (PMID 22384047, 2012).
chordoma (1 paper, 2023). Chordomas are rare malignant tumors arising from embryonic remnants of the notochord in axial skeleton. "As MTAP and TYMS are involved in important cellular processes, inhibition or loss of these genes have a major impact on the cellular processes and can possibly be explored further for use as therapeutic targets in chordoma." (PMID 37147496, 2023).
chronic myeloid leukemia (1 paper, 2023). "We have previously shown that decitabine, following intracellular modification, binds to TYMS using a high throughput CETSA-based screen with the K562 chronic myeloid leukemia cell line." (PMID 36380143, 2023).
ectodermal dysplasia (1 paper, 2022). "Previously, a genetic linkage study on a large consanguineous Pakistani family, where affected members manifested clinical features of syndromic ectodermal dysplasia [ECTD (MIM: 616029)], has revealed a linkage candidate region on chromosome 18p11.32-p11.3, which includes the TYMS-ENOSF1 locus." (PMID 35931051, 2022).
endometrial cancer (1 paper, 2022). Primary or metastatic malignant neoplasm involving the endometrium (mucous membrane that lines the endometrial cavity). "rs3819102, located in the 3′‐flanking region of TYMS, was reported to increase the risk of endometrial cancer in the Chinese population." (PMID 35499292, 2022).
fibrosarcoma (1 paper, 2023). A malignant mesenchymal fibroblastic neoplasm affecting the soft tissue and bone. "TYMS expression in these mice did not increase the overall incidence of fibrosarcoma, although we observed 2-fold higher fibrosarcoma incidence in hTS/Ink4a/Arf−/− females compared to control Ink4a/Arf−/− females (15.2% vs 7.1% respectively)." (PMID 37106126, 2023).
follicular thyroid cancers (1 paper, 2022). "We finally constructed glycolysis risk score (GRS) predictive models based on four targeting genes (ADM, CD44, MKI67 and TYMS), which were highly upregulated in tumor samples, including papillary and follicular thyroid cancers." (PMID 35528004, 2022).
heart failure (1 paper, 2024). Inability of the heart to pump blood at an adequate rate to meet tissue metabolic requirements. "A total of 24 small molecule drugs targeting TYMS were predicted, including Raltitrexed, Floxuridine, Pemetrexed, Capecitabine, Fluorouracil, contributing to the development of new therapeutic targets for dialysis patients heart failure." (PMID 39844908, 2024).
leukopenia (1 paper, 2023). "Previous studies have shown an inverse relationship between TYMS expression levels and MTX toxicity, indicating that higher TYMS levels are associated with lower MTX toxicity and higher TYMS levels are associated with a decreased risk of leukopenia." (PMID 37384310, 2023).
liver fibrosis (1 paper, 2024). "Moreover, compared to liver fibrosis stages F0 to F2, AKR1B10, and TYMS exhibited increased expression in fibrosis stages F3 to F4." (PMID 38720280, 2024).
mesenchymal tumors (1 paper, 2023). "In summary, our data suggests that TYMS expression results in more aggressive phenotype with higher incidence of hematological and mesenchymal tumors in the same mouse." (PMID 37106126, 2023).
mucinous ovarian carcinoma (1 paper, 2018). An invasive malignant neoplasm that arises from the ovary and is characterized by the presence of malignant epithelial cells that contain intracytoplasmic mucin and may resemble the epithelial cells of the endocervix or gastrointestinal tract. "We sought to replicate our previously reported association between rs495139 in the TYMS-ENOSF1 3′ gene region and increased risk of mucinous ovarian carcinoma (MOC) in an independent sample." (PMID 30134598, 2018).
non-Hodgkin lymphoma (1 paper, 2023). Distinct from Hodgkin lymphoma both morphologically and biologically, non-Hodgkin lymphoma (NHL) is characterized by the absence of Reed-Sternberg cells, can occur at any age, and usually presents as a localized or generalized lymphadenopathy associated with fever and weight loss. "To confirm this finding and to compare TYMS levels among different non-Hodgkin lymphoma transcriptomes, we used a different dataset that showed B and T cell lymphomas (n = 32) express high TYMS levels that correlated with low levels of CDKN2A expression." (PMID 37106126, 2023).
oral mucositis (1 paper, 2016). Inflammation of the mucous membranes of any of the structures in the mouth. "TYMS was also found to be associated with oral mucositis in patients receiving hematopoetic cell-transplantation." (PMID 27618021, 2016).
ovarian tumor (1 paper, 2018). "Interestingly, the mean expression of the three genes (TYMS, ZEB2, and MDM2) was upregulated in all ovarian tumor subtype analyzed." (PMID 30038317, 2018).
pancreatic ductal adenocarcinoma (1 paper, 2023). An infiltrating adenocarcinoma that arises from the epithelial cells of the pancreas. "However, inhibition of TYMS by 5-FU alone or when combined with other cytotoxic agents in the FOLFIRINOX regimen is consistently associated with induction of TYMS overexpression, resulting in acquired drug resistance in patients with pancreatic ductal adenocarcinoma (PDAC)." (PMID 37097751, 2023).
peritoneal cancers (1 paper, 2023). A peritoneum cancer that is located in the inside of the abdomen. "For example, TYMS, an enzyme involved in the synthesis of thymidine, is upregulated in peritoneal cancers and is associated with poor prognosis." (PMID 37233659, 2023).
prostate adenocarcinoma (1 paper, 2024). "A differential survival analysis carried out with GEPIA showed the correlation of ZWINT, CDK1, IGFPB3, and TYMS expression with disease-free survival (DFS) in a database of patients with prostate adenocarcinoma." (PMID 38542079, 2024).
prostate tumors (1 paper, 2015). "Two earlier studies analyzing 52 and 79 prostate tumors by immunohistochemistry had reported TYMS positivity in 67% and in 100% of cancers." (PMID 25762627, 2015).
subcutaneous tissue disorder (1 paper, 2025). A disease involving the superficial fascia. "On the other hand, the 3R genotype of TYMS 5'UTR (rs45445694) is associated as a risk factor for skin and subcutaneous tissue disorders (OR = 6.40; p = 0.029)." (PMID 40786508, 2025).
synovial sarcoma (1 paper, 2025). "Concomitantly, genes activated by SS18::SSX in synovial sarcoma were repressed, including HOX genes HOXC6, HOXA10 as well as SRSF1 and TYMS." (PMID 40804185, 2025).
temporal lobe epilepsy (1 paper, 2024). A localization-related (focal) form of epilepsy characterized by recurrent seizures that arise from foci within the temporal lobe, most commonly from its mesial aspect. "Increased TYMS leukocyte gene expression is prognostic for high seizure frequency temporal lobe epilepsy and also fits with the mechanism of increased homocysteine protein levels, facilitation of NMDA signaling and increased epileptogenicity." (PMID 38166692, 2024).
teratoma (1 paper, 2024). A non-seminomatous germ cell tumor characterized by the presence of various tissues which correspond to the different germinal layers (endoderm, mesoderm, and ectoderm). "In summary, we found that TYMS−/− cells produce proliferative teratomas in vivo, similar to those obtained with TYMS+/+ cells only under dTMP supplementation." (PMID 38867450, 2024). "TYMS+/+-hiPSC produced teratoma-like growth in all mice regardless of the thymidine supplementation, while TYMS−/−-hiPSCs produced visible teratomas only under dTMP supplementation." (PMID 38867450, 2024). "Only one mouse presented a small TYMS−/−-derived teratoma without supplementation, composed mainly of primitive glial, epithelial, and mesenchymal tissue." (PMID 38867450, 2024).
thyroid carcinomas (1 paper, 2019). "Further survival analysis showed that high expression of TOP2A, TYMS, FEN1, PRC1, or UBE2C gene significantly decreased disease-free survival of patients with other thyroid carcinomas." (PMID 30774662, 2019). "Survival analysis indicated that high expression of TOP2A, TYMS, FEN1, PRC1, or UBE2C gene significantly decreased disease-free survival of patients with other thyroid carcinomas." (PMID 30774662, 2019). "TCGA data suggested that the expression levels of TOP2A, TYMS, FEN1, and PRC1 genes were also upregulated in other histological subtypes of thyroid carcinoma." (PMID 30774662, 2019). "High expression of TOP2A, TYMS, FEN1, PRC1, or UBE2C gene significantly decreased disease-free survival of patients with other thyroid carcinomas." (PMID 30774662, 2019). "Results suggested that the expression levels of hub genes, TOP2A, TYMS, FEN1, and PRC1, were also upregulated in at least one histological subtype of thyroid carcinoma." (PMID 30774662, 2019).
ventricular septal defect (1 paper, 2012). The presence of a defect (opening) in the septum that separates the two ventricles of the heart. "This hypothesis could be corroborated by the results of the exon's sequencing of TYMS in the same examined samples, where no case of missense mutation has been found in the TYMS entire coding region of 200 ventricular septal defect samples (data not shown)." (PMID 22384047, 2012).
cancer (276 papers, 1995 to 2025). A tumor composed of atypical neoplastic, often pleomorphic cells that invade other tissues. "TYMS encodes an enzyme that has been widely studied as a target for cancer chemotherapy, particularly as the primary site of action for drugs like 5-fluorouracil (5-FU) and folate analogs." (PMID 41244050, 2025). "Overexpression of TYMS is associated with resistance to 5-FU and poor prognosis in colorectal, breast, and other cancers." (PMID 41244050, 2025). "Current studies shown that elevated TYMS mRNA and protein levels were associated with anti-cancer drug resistance or worse clinical prognosis in a variety of hematological and solid tumors." (PMID 39844908, 2024). "We previously showed that overexpression of TYMS in transgenic mice induced the development of tumors after a long latency, suggesting that aberrantly elevated TYMS cooperates with other cancer gene mutations to drive the neoplastic process." (PMID 37106126, 2023). "Accumulating evidence has demonstrated that TYMS expression inversely associates with 5-FU sensitivity and efficacy in cancer cells." (PMID 36759799, 2023). "Elevated TYMS expression has been reported as a poor prognostic biomarker in many cancer subtypes, and somatic mutational or epigenetic silencing of the INK4a/ARF locus is one of the most common oncogenic events in human cancers." (PMID 37097751, 2023). "Here we report the cooperation of ectopic expression of human TYMS with loss of Ink4a/Arf, one of the most commonly mutated somatic events in human cancer." (PMID 37106126, 2023). "It should be noted that the elevated level of TYMS expression was also associated with more invasive and metastatic abilities of cancer cells." (PMID 35740289, 2022). "TYMS also seems to be associated with cancer metastasis and acquiring mesenchymal character by tumor cells during epithelial–mesenchymal transition (EMT)." (PMID 35740289, 2022). "Variant rs151264360 in TYMS gene has also been widely studied regarding cancer treatment in different regions." (PMID 35678683, 2022). "The active metabolite of 5-Fluorouracil (5FU), used in the treatment of several types of cancer, acts by inhibiting the thymidylate synthase encoded by the TYMS gene, which catalyzes the rate-limiting step in DNA replication." (PMID 35922756, 2022). "TYMS is located on chromosome 18p, encoding an enzyme involved in DNA replication and repair, and its function in malignant tumor cells has been reported." (PMID 34141464, 2021). "Recent studies have been reported that TYMS is a biomarker with diagnostic and prognostic value in a variety of cancers." (PMID 34141464, 2021). "We also highlighted the association of TYMS 3R/3R genotype carriers with relapse-free cancer protection and survival time." (PMID 33369477, 2020). "In this work, we describe the effects of a PPRH targeting a polypyrimidine strand complementary to a newly identified G4 motif present in the 5’UTR of the TYMS gene, whose encoded protein is a classical anti-cancer target due to its role in DNA synthesis." (PMID 32708710, 2020). "Apart from TYMS genetic polymorphisms, various miRNAs play a crucial role in altering sensitivity of cancer cells to 5-FU." (PMID 33087811, 2020). "Previous studies have reported that CA9, EXTL2, PGAM1, and TYMS were dysregulated across multiple human cancers and intricately associated with tumorigenesis by functioning as key enzymes underlying metabolism." (PMID 33425725, 2020). "Mutations in its enhancer region, resulting in an overexpression of TYMS, are associated with several cancers and response to chemotherapy." (PMID 31266445, 2019). "5-FU inhibits cancer cell growth by disrupting action of thymidylate synthase (TYMS), thereby causing DNA and RNA damage." (PMID 26416450, 2015).